FOXQ1 (forkhead box Q1)
Description:
Plays a role in hair follicle differentiation.
Synonyms: HFH1
Tractability: No criterion of Open Targets' tractability assessment is met for any kind of drug.
Gene: Protein-coding gene on chromosome 6 (1,312,098 to 1,314,758, forward strand). Ensembl gene ENSG00000164379.
Subcellular location: Nucleus
Subcellular location (Human Protein Atlas): Nucleoplasm; Nuclear bodies; Nucleoli fibrillar center
Pathways (Reactome):
Cell-Cell communication: Negative Regulation of CDH1 Gene Transcription
Gene Ontology:
Molecular function: sequence-specific double-stranded DNA binding; DNA-binding transcription factor activity, RNA polymerase II-specific; RNA polymerase II cis-regulatory region sequence-specific DNA binding; DNA-binding transcription factor activity; DNA-binding transcription repressor activity, RNA polymerase II-specific; sequence-specific DNA binding
Biological process: anatomical structure morphogenesis; cell differentiation; regulation of transcription by RNA polymerase II; negative regulation of transcription by RNA polymerase II; regulation of DNA-templated transcription
Cellular component: chromatin; nucleoplasm; nucleus
Genetic constraint (gnomAD): Loss-of-function variants: 1 observed, 0.28 expected, observed/expected ratio (o/e) 3.57. That is too few expected variants to judge how well the gene tolerates losing a copy. Missense variants: 640 observed, 385.15 expected, observed/expected ratio (o/e) 1.66, 90% interval 1.56 to 1.77. Synonymous variants: 343 observed, 203.81 expected, observed/expected ratio (o/e) 1.68, 90% interval 1.54 to 1.84.
Homologues: Orthologues: macaque FOXQ1 (95% identical), chimpanzee FOXQ1 (88% identical), mouse Foxq1 (76% identical), pig FOXQ1 (75% identical), rat Foxq1 (68% identical), zebrafish foxq1b (40% identical), tropical clawed frog FOXQ1 (39% identical), zebrafish foxq1a (36% identical). Paralogues in human: FOXM1 (26% identical), FOXC2 (22% identical), FOXC1 (21% identical), FOXD3 (21% identical), FOXD1 (21% identical), FOXE1 (21% identical), FOXD2 (20% identical), FOXL2 (20% identical), FOXD4 (20% identical), FOXA2 (20% identical), FOXI3 (20% identical), FOXA1 (19% identical), and 29 more.
Diseases named in the same sentence as FOXQ1 in open-access papers:
FOXQ1 is named in the same sentence as 95 diseases in open-access papers, as found by Europe PMC text mining. Sharing a sentence is not in itself a finding about the gene and the disease. The quoted sentences say what the papers report.
breast carcinoma (44 papers, 2012 to 2025). "SOX2, YB1, and FOXQ1 are all transcription factors associated with signaling pathways that are constitutively activated in breast cancer, particularly TNBC, including Wnt/B-catenin, Hedgehog, and Notch, which regulate the maintenance and survival of CSCs." (PMID 40432134, 2025). "Nonetheless, a pooled loss-of-function experiment of putative EMT regulators in breast cancer cell lines supports a critical role of FOXQ1 in EMT." (PMID 39777582, 2025). "FOXQ1 was reported to be expressed in many epithelial cell lines and to be associated with epithelial to mesenchymal transition in breast cancer making it a good candidate for studies also in CRC." (PMID 38156105, 2023). "FOXQ1 has been reported to be implicated in breast cancer EMT and metastasis, negative regulation of CDH1 expression is one of the mechanisms." (PMID 32332873, 2020). "Recent studies have clearly showed that Foxq1 was implicated in tumor proliferation and metastasis in colorectal cancer, glioblastoma, breast cancer and hepatocellular carcinoma." (PMID 25098939, 2014). "Forkhead box Q1 (Foxq1, fold change 6.7) gene expression was correlated with high-grade basal-like breast cancers where it was associated with metastases and poor clinical outcomes." (PMID 23148692, 2012). "It has been proposed that platelet-derived growth factor receptors are key players in the chemoresistance of breast cancer caused by FOXQ1, which could have consequences for the evolution and maturation of novel therapeutic regimens for the disease." (PMID 37626655, 2023). "FOXQ1 protein expression is significantly higher in triple-negative breast cancer samples than in normal mammary tissues, so it is a novel target of breast cancer stem cells’ inhibition by diallyl trisulfide." (PMID 41347087, 2025). "In contrast to other cancers like colorectal cancer, where low FOXQ1 expression often signifies a favorable prognosis, the opposite is true for breast cancer." (PMID 40003882, 2025). "FOXQ1, as a transcription regulator, mediates the biological function of multiple genes in breast cancer, so it is a key target for chemical and biological targeted therapy." (PMID 41347087, 2025). "The RNA-binding protein Hu antigen R (HuR) is upregulated and is a direct target that regulates FOXQ1 in human breast cancer." (PMID 41347087, 2025). "For instance, FOXH1 and FOXQ1 in lung, colorectal, and breast cancer promote EMT by controlling proliferation, migration, and invasion through downregulation of E‐cadherin." (PMID 40099944, 2025). "Studies on breast cancer have revealed that the overexpression of FOXQ1 in breast cancer cells leads to increased levels of circ_0000643 by binding to its host gene promoter region." (PMID 38994627, 2024). "FOXQ1 knockdown increases breast cancer ferroptosis and inhibits oncogenesis via the FOXQ1/circ_0000643/miR-153/SLC7A11 axis." (PMID 38778030, 2024). "In this study, we discovered that activation of FGFR1 signaling significantly upregulates the oncogenic transcription factor FOXQ1 through the FGFR1-ERK2-c-FOS gene regulatory axis in breast cancer cells." (PMID 36778115, 2023). "In breast cancer, it was discovered that miR-937 directly targets the forkhead box Q1 (FOXQ1) mRNA, and FOXQ1 was shown to be overexpressed, and this overexpression exhibited a negative correlation with miR-937 expression." (PMID 37626655, 2023). "In contrast, the knockdown of FOXQ1 inhibited the role of FGFR1 signaling in the stimulation of breast cancer cell proliferation and colony formation in culture, as well as the growth of human breast cancer cell-derived xenografts in mice." (PMID 36778115, 2023). "Compared with c-FOS, FOXQ1 is an understudied protooncogenic transcription factor for its upstream regulators, downstream direct target genes, and mechanism-based roles in breast cancer 29-31." (PMID 36778115, 2023).
breast carcinoma (continued). "Knockdown of FOXQ1 expression effectively prevented FGFR1-promoted breast cancer cell growth in culture and tumor growth in vivo." (PMID 36778115, 2023). "When compared to healthy mammary tissues, the production of the FOXQ1 protein was considerably increased in cases of basal-like breast cancer." (PMID 37626655, 2023). "In this study, we demonstrated that activation of the FGFR1 signaling robustly upregulated FOXQ1 mRNA and protein expression in breast cancer cells." (PMID 36778115, 2023). "Activation of the ERK2/c‐Fos/forkhead box Q1 (FOXQ1) pathway plays a key role in the growth of breast cancer cells." (PMID 37750089, 2023). "Next, we sought to determine the mechanism by which RAPH1-i3 and FOXQ1 regulate the aggressiveness of breast cancer cells." (PMID 38062011, 2023). "Expression of FOXQ1 has been found to be significantly correlated with highly aggressive basal-like breast cancers with poor clinical outcome." (PMID 34708244, 2022). "A subset of 109 genes exhibited a significant Spearman correlation (R > 0.2) with FOXQ1 across breast cancer samples." (PMID 36319643, 2022). "Here the authors show that FOXQ1 recruits the KMT2/MLL histone methyltransferase complex as a transcriptional coactivator to activate EMT programme in breast cancer." (PMID 36319643, 2022). "For instance, FOXQ1 has been considered as a novel target of breast cancer stem cell inhibition; Han et." (PMID 35183223, 2022). "We next utilized TCGA and METABRIC breast cancer datasets to explore the correlation of DDR2 with other components of the shared FOXQ1-SNAIL gene set." (PMID 36713812, 2022). "Forkhead Box Q1 (FoxQ1) is a pro-tumorigenic factor whose gene shows subtype-specific differences in expression levels in breast cancers." (PMID 36078038, 2022). "On the other hand, previous studies have suggested that FOXF2 and FOXQ1 play opposite roles in controlling epithelial-mesenchymal transition and visceral metastasis in basal-like breast cancer cells." (PMID 33898467, 2021). "While recent in vitro study suggested that FOXF2 binds to the promoter and represses the expression of FOXQ1 in a breast cancer cell line, our in vivo data demonstrated a cis-regulation of Foxq1 expression by the Foxf2 gene disruption." (PMID 33898467, 2021). "We also demonstrate that FOXQ1 is one of the downstream targets that contribute to HuR’s role in breast cancer invasion." (PMID 32332873, 2020). "Previous studies have demonstrated that FOXQ1 is increased and functions as an oncogene in several cancers, such as hepatocellular carcinoma, breast cancer and colorectal cancer." (PMID 32061262, 2020). "Later identified as an oncogene, FOXQ1 is highly expressed in colorectal cancer, breast cancer, liver cancer, and various other cancers, and multiple studies have demonstrated a close relationship between FOXQ1 and Wnt/β-catenin in cancer cells." (PMID 32943107, 2020). "BITC also was able to repress EMT partially through Forkhead Box Q1 (FOXQ1) suppression in both breast cancer cells (2.5 μM and 5 μM) and xenografts (7.5 μmol BITC/mouse), thus reducing their metastatic potential." (PMID 31003534, 2019). "Some genes, well-known in breast cancer subtyping and involved in the cancer-relevant pathways, are the hubs of the network, e.g., FOXQ1, SFRP1 and ESR1." (PMID 27786176, 2016). "Oncogene FOXQ1 is overexpressed in a series of tumors, such as hepatocellular carcinoma, breast cancer, and colorectal cancer and becomes a potential bio-marker in prognosis." (PMID 27363024, 2016). "Towards the goal of understanding breast cancer metastasis, our group performed a cross-species expression profiling and identified Foxq1 as an EMT- and metastasis-promoting gene in breast cancer." (PMID 26583906, 2015). "For example, FOXQ1 is an oncogene found overexpressed in colorectal and breast cancer, where it induces proliferation, dedifferentiation and EMT." (PMID 26022688, 2015).
breast carcinoma (continued). "FOXC1, FOXC2, and FOXQ1 are highly expressed in basal-like subtype breast cancer, but are less present in luminal subtype cancer." (PMID 25848863, 2015). "We identified and validated several known metastasis mediators as regulated by MMP9, including Foxq1 and PLAU, as well as the suspected breast cancer susceptibility gene BRIP1." (PMID 24811362, 2014). "Several recent studies demonstrated the correlation between increased FoxQ1 expression with poor prognosis for many human cancers, including breast cancer, hepatocellular carcinoma and colon cancer." (PMID 25356753, 2014). "This is consistent with recent studies reporting FoxQ1 overexpression in breast cancer and colorectal cancer, and that high expression of FoxQ1 enhanced tumorigenicity and tumor growth." (PMID 25356753, 2014). "Although previous studies have suggested that FoxQ1 plays an important role in the tumorigenesis of several malignancies, including non-small cell lung cancer, breast cancer, and colorectal cancer, its role and molecular mechanisms in glioma are not known." (PMID 23383267, 2013). "Recently, accumulating evidence has shown that FoxQ1 to be a valuable prognostic indicator for poor outcome in patients with breast cancer and non-small cell lung cancer." (PMID 23383267, 2013). "Recently, accumulating evidence suggests that human FoxQ1 plays a key role in regulating the EMT of breast cancer, and aggressiveness in colon cancer." (PMID 22761930, 2012). "Recent studies have described that FOXQ1 has been found to be overexpressed in colorectal cancer and breast cancer, in which patients have poor clinical outcomes." (PMID 22761930, 2012). "Recent studies have confirmed that FoxQ1 to be a valuable prognostic indicator for poor survival in breast cancer." (PMID 22761930, 2012). "Several studies have reported increased expression of FOXQ1 in breast cancer cells." (PMID 40630951, 2025). "Several studies reported increased FOXQ1 expression in breast cancer cells." (PMID 39777582, 2025). "Interestingly, while no such screen has been reported to date, a similar experimental approach identified an inhibitor of the RNA binding protein HuR that decreased the abundance of FOXQ1 mRNA in breast cancer cells." (PMID 39777582, 2025). "However, benzyl isothiocyanate as a breast cancer chemoprevention agent regulates FOXQ1 expression and mediates the inhibition of EMT in human breast cancer cells." (PMID 41347087, 2025). "However, in certain subtypes of breast cancer, i.e., HER2-positive breast cancer and ductal breast cancer, the level of FOXQ1 expression is lower compared to healthy tissue and triple-negative breast cancer." (PMID 40630951, 2025). "Additionally, miR-937 acts as an inhibitor to directly target and regulate FOXQ1, thereby limiting breast cancer cell expansion and cancer progression." (PMID 41347087, 2025). "Similarly, Nuclear isoform of RAPH1 (named RAPH1-i3) interacts with FOXQ1 and can promote breast cancer progression and radio-resistance." (PMID 41347087, 2025). "The expression of FOXQ1 varies across different types of breast cancer." (PMID 40003882, 2025). "Phosphorylation of FOXQ1 at S248 has also been observed in high-throughput proteomics assays of breast cancer samples, suggesting that this PTM may be relevant for other types of cancer as well." (PMID 39777582, 2025). "Moreover, FOXQ1 has been a potential prognostic and biomarker for a variety of cancers, such as colorectal cancer and breast cancer, but the research on orthopedic disease is extremely rare." (PMID 38503493, 2024). "In this study, we found that activation of the FGFR1 signaling enhances the phosphorylation of both ERK1 and ERK2, and inhibition of MEK to prevent the activation of both ERK1 and ERK2 blocked the FGFR1 signaling-induced FOXQ1 upregulation and breast cancer cell proliferation." (PMID 36778115, 2023).
breast carcinoma (continued). "Interestingly, knockout of ERK2, but not ERK1, specifically suppressed the FGFR1 signaling-induced FOXQ1 expression and breast cancer cell proliferation." (PMID 36778115, 2023). "In this study, we demonstrated that the human FOXQ1 gene promoter contains a functional AP-1 binding motif that is associated with c-FOS and required for bFGF-stimulated transcriptional activity of the FOXQ1 gene promoter in breast cancer cells." (PMID 36778115, 2023). "Diallyl Trisulfide’s targeting of FOXQ1 prevents breast cancer stem cells from proliferating." (PMID 37626655, 2023). "Targeting RAPH1-i3 and FOXQ1 may provide a therapeutic strategy for improving radioresistance in breast cancer." (PMID 38062011, 2023). "RAPH1-i3 and FOXQ1 represent therapeutic targets for the treatment of breast cancer including TNBC." (PMID 38062011, 2023). "Therefore, FOXQ1 is one of the HuR direct mRNA targets that contributes to HuR’s role in breast cancer invasion and metastasis, potentially through promoting epithelial-to-mesenchymal transition." (PMID 32332873, 2020). "Suppression of FoxQ1 in benzyl isothiocyanate-mediated inhibited EMT in human breast cancer cells." (PMID 25356753, 2014). "Moreover, overexpression of FoxQ1 has been reported in several cancers including lung cancer, pancreatic ductal adenocarcinomas, colorectal cancer and breast cancer." (PMID 23383267, 2013). "Recently, it was shown that FOXQ1 increased tumorigenesis of colon and breast cancer cells." (PMID 23555880, 2013). "This discrepancy could be attributed to the role FOXQ1 plays in the EMT process in breast cancer." (PMID 40003882, 2025). "However, it remains unclear whether the FGFR1 signaling pathway can promote breast cancer growth by regulating FOXQ1 expression." (PMID 36778115, 2023). "Hence, FOXQ1 may also contribute to HuR’s role in breast cancer invasion and metastasis via increasing the expression of protein that degrades ECM." (PMID 32332873, 2020). "Forkhead Box Q1 (FoxQ1) might be another novel target of DATS in breast cancer stem cell." (PMID 28698459, 2017). "Another transcriptional repressor of FOXQ1 is the related protein FOXF2, and in fact, FOXQ1 and FOXF2 were found to trans-repress each other in breast cancer cells as well as during embryonic development." (PMID 39777582, 2025). "According to recent research, diallyl trisulfide has shown anticancer effects in breast cancer stem cells by decreasing ALDH activity and down-regulating forkhead box Q1 (FOXQ1) protein activity." (PMID 39859345, 2025). "By activating of the FGFR1-MEK-ERK2-c-FOS signaling axis, FOXQ1 expression is upregulated, FOXQ1 is an essential factor mediating the FGFR1 signaling and promotes breast cancer worsening." (PMID 41347087, 2025). "FOXQ1 also upregulates ZEB2 and versican V1 to enhance the invasiveness of hepatocellular carcinoma cells 27 and the stemness and drug resistance of breast cancer cells." (PMID 36778115, 2023). "Since FGFR1 signaling upregulates FOXQ1 gene expression mainly through activating ERK2, we examined how the knockout of ERK2 or ERK1 affects FGFR1 signaling-promoted breast cancer cell growth." (PMID 36778115, 2023). "Similar findings were observed in estrogen receptor-positive breast cancer cell lines that had co-expression of RAPH1-i3 and FOXQ1." (PMID 38062011, 2023). "Previous studies have reported that FOXQ1 can activate EMT and promote metastasis and chemoresistance in breast cancer." (PMID 38062011, 2023). "Consistent results were also obtained from MDA-MB-231 breast cancer cells with endogenous FGFR1 protein expression, in which the bFGF-induced FOXQ1 mRNA and protein expression can be blocked by MEK/ERK inhibitors but not by AKT inhibitors." (PMID 36778115, 2023). "The forkhead box (FOX) transcription factor FOXQ1 plays an important role in EMT and chemoresistance of breast cancer cells." (PMID 38062011, 2023).